LAIR1 (leukocyte associated immunoglobulin like receptor 1)
Diseases named in the same sentence as LAIR1 in open-access papers (continued):
Sharing a sentence is not in itself a finding about the gene and the disease.
tumor (continued). "An immunosuppressive TME, potentially fostered by elevated CNOT7 activity, might lead to an upregulation or enhanced function of LAIR-1, thereby promoting NK cell anergy or exhaustion and contributing to tumor progression and immune evasion." (PMID 40806280, 2025). "LAIR1-knockout (Lair1–/–) mice show enhanced immunity against tumor." (PMID 40591413, 2025). "LAIR1 expression was localized to the tumor and perivascular regions in HGG." (PMID 38357919, 2024). "In cancer, impaired LAIR-1 mediated inhibition could lead to inflammation in inappropriate sites, depending on the citrullinated collagen location within the tumor." (PMID 38659022, 2024). "Collagen deposition in tumors could therefore protect tumor cells from the immune system through LAIR-1." (PMID 38659022, 2024). "Again, tumour growth and overall survival were similar in Lair1+/+ and Lair1−/− mice." (PMID 38236251, 2024). "Here, we investigated the role of LAIR-1 in anti-tumour responses." (PMID 38236251, 2024). "LAIR-1 can also inhibit immune cells through tumour-derived collagens and collagen fragments." (PMID 38236251, 2024). "In addition to collagen facilitating tumor invasion and providing a niche for cancer stem cells, collagen has also been shown to trigger immune suppression through LAIR1-mediated T cell exhaustion and alternative activation of macrophages." (PMID 38357919, 2024). "Leukocyte-Associated Ig-like Receptor-1 (LAIR1) is an ITIM-bearing immune-IR expressed by the majority of immune cells, including T cells, B cells, NK cells, monocyte/macrophages, neutrophils, pDCs, as well as by tumor cells." (PMID 38504978, 2024). "Thus, additional targeting of the LAIR-1:collagen pathway with NC410 is a promising approach to treating tumours where conventional immunotherapy is ineffective." (PMID 38236251, 2024). "LAIR-1 was observed to be expressed on pan CK+ tumor cells and CD14+ monocytes." (PMID 36960400, 2023). "The spatial, quantitative assessment of LAIR-1 in NSCLC shows positive association of OS with high LAIR-1+/CD68+ cell densities and negative association of OS with high LAIR-1 expression in LUAD tumor subtype." (PMID 36960400, 2023). "Tumor and stroma LAIR-1 expression were observed in both the discovery and validation cohorts." (PMID 36960400, 2023). "With regards to overall survival in both cohorts, we observed a significant association with high LAIR-1 tumor expression and worse outcome in LUAD cases and but not in LUSC cases." (PMID 36960400, 2023). "Tumours often overexpress LAIR-1, thereby evading the immune system." (PMID 37373151, 2023). "The expression pattern of LAIR-1 in human NSCLC was detected in both tumor and stromal cells." (PMID 36960400, 2023). "Moreover, heat‐map analysis also indicated that the concentration of 29 types of tumor‐infiltrating immune cells or molecules in the patients with high expression of LAIR‐1." (PMID 35702880, 2023). "LAIR‐1 is exactly highly enriched in macrophages, which may be involved in the immune escape and invasion of tumor cells." (PMID 35702880, 2023). "Moreover, the significance of LAIR-1 in immune suppression is emphasized by its presence on dendritic cells and macrophages, which impacts the immune response of tumor-specific T cells." (PMID 38332915, 2023). "LAIR1 is a collagen receptor expressed by the majority of immune cells, including T cells, B cells, NK cells, monocytes, neutrophils, macrophages, and pDCs, as well as tumor cells." (PMID 36555775, 2022). "Overall, CD4+, CD8+, CD19+, and CD11b+Ly6G+ subsets had fewer LAIR-1+ cells, while NK cells, NKT cells, CD11b+Ly6Chi cells, and CD11b+F4/80hi macrophages had higher percentages of LAIR-1+ cells, particularly at the tumor site compared with the spleen and blood." (PMID 35230974, 2022).
tumor (continued). "In addition to providing a physical obstacle to immune cells, collagens can also bind to the inhibitory receptor LAIR-1, which is expressed across multiple immune cell subsets and correlates with poor prognosis in several tumor types." (PMID 35230974, 2022). "In addition, from a clinical point of view, the level of expression of LAIR1 has been correlated with tumor aggressiveness." (PMID 36555775, 2022). "We further studied LAIR1 blockade in human tumor development in humanized mice." (PMID 36211388, 2022). "Furthermore, when expressed by tumor cells, LAIR1 can modulate their proliferation or invasion properties, with contradictory pro- or anti-tumoral effects depending on tumor type." (PMID 36555775, 2022). "The high expression of LAIR1 at the mRNA level in clinical samples was positively correlated with collagens, suggesting that the high expression of collagens within the tumor microenvironment may lead to pro-tumoral responses via LAIR1." (PMID 36555775, 2022). "NC410 bound to collagen-rich areas where LAIR-1+ immune cells were localized in the tumor." (PMID 36159809, 2022). "Understanding LAIR-1 and collagen expression in the context of tumor structure and co-localization could help to identify indications that may best benefit from targeting this axis." (PMID 34121658, 2021). "We hypothesized that alterations in expression and remodeling of collagen in the TME regulate the threshold of T cell activation through LAIR-1 and are employed by tumor cells to escape immune surveillance." (PMID 34121658, 2021). "This indicated that an abundance of collagen may trap immune cells in the tumor stroma, possibly by binding to LAIR-1." (PMID 34121658, 2021). "Further studies are needed to elucidate the role of LAIR-1 in the immunosuppressive tumor microenvironment, but based on current knowledge, LAIR-1 could be a promising cancer therapeutic target." (PMID 34956223, 2021). "In summary, this study provides support for utilizing NC410, a novel LAIR-2 Fc fusion protein that promotes T cell activity, as a supplemental therapy to induce anti-tumor immunity in collagen-rich, immune-excluded tumors in which excluded immune cells express high levels of LAIR-1." (PMID 34121658, 2021). "LAIR-1 expression is observed in all tumor types and largely restricted to immune cells." (PMID 34121658, 2021). "As collagens play a major role in tumour progression, collagen-mediated stimulation of LAIR-1 may activate ITIMs, resulting in the inhibition of immune cell activity." (PMID 33396670, 2020). "Remarkably, the upregulation of collagen expression by tumor cells and/or tumor stroma could lead to the downregulation of anti-tumor responses mediated by the inhibitory collagen receptor LAIR-1 expressed on NK cells and other effector immune cells." (PMID 33013909, 2020). "Altogether, these findings identify an association between LAIR-1 and HER2+ expression and suggest a regulatory role which might result in tumour proliferation/invasion leading to a poor patient outcome." (PMID 33396670, 2020). "We focus here on the critical immune checkpoint PD-1 and on Siglec-7/p75/AIRM1/CD328, LAIR-1/p40/CD305, and IRp60/CD300a, originally identified in our labs, representing additional immune checkpoints possibly dampening anti-tumor NK cell responses in given pathological settings." (PMID 33013909, 2020). "However, the detailed mechanism underlying LAIR-1 action and its relationship with ETS family members in normal and tumor cells is unclear." (PMID 29915163, 2018). "Above results indicate that different ETS factors may modulate the LAIR-1 in specific immune cells or tumor cells." (PMID 29915163, 2018). "An interesting implication of the discovery of LAIR-1 as an inhibitory collagen receptor is that tumor cells, known to upregulate collagen expression, may use this interaction to downregulate anti-tumor responses." (PMID 23691008, 2013).
tumor (continued). "In this context, NC410, a dimeric LAIR2-Fc fusion protein that blocks collagen binding to LAIR1, has shown the ability to stimulate human T cell expansion in a xenogeneic graft-versus-host disease model and enhance T cell-mediated antitumor immunity in a humanized tumor model." (PMID 40563506, 2025). "Therefore, we have identified an immunosuppressive loop involving LAIR1 in the TME, which can be represented as follows: LAIR1 expression on M2-like MΦ↑ → FXIII-A secretion↑ → collagen IV deposition/proliferation↑ → activation of LAIR1+ M2-like MΦ↑ → tumor immunosuppression↑." (PMID 40591413, 2025). "However, combined targeting of LAIR-1 and PD-L1 results in increased tumour control." (PMID 38236251, 2024). "However, since LAIR1 is widely expressed also by tumor cells, where it may induce either proliferation or inhibition depending on the tumor type, its therapeutic exploitation needs to be carefully tailored to each specific cancer microenvironment." (PMID 38504978, 2024). "Therefore, the mechanism of tumor regulation by LAIR‐1 is worthy of further study." (PMID 37647449, 2023). "In addition, high expression of LAIR‐1 is highly correlated with the malignant degree of the tumor." (PMID 35702880, 2023). "Thus, the mechanism of HCC tumor regulation by LAIR‐1 deserves further investigation." (PMID 37647449, 2023). "In addition, we noted that LAIR-1 is highly expressed on tumor cells." (PMID 36960400, 2023). "Targeting LAIR-1 through the inhibitory protein tyrosine phosphatase SHP-1 signaling could sensitize tumors resistant to PD-1/PD-L1 axis blockade which leads to the reduction of tumor growth and metastasis in the mouse model." (PMID 36960400, 2023). "Similarly, we observed the association of tumor but not stromal LAIR-1 expression with OS in the LUAD subtype of the validation cohort as well (HR = 2; *, P = 0.05)." (PMID 36960400, 2023). "Due to the high expression of Tgfbr2 and LAIR-1 in MC38 tumor–infiltrating macrophages, we hypothesized that blockade of LAIR-1 signaling via NC410 could synergize with TGF-β inhibition mediated by bintrafusp alfa to remodel the myeloid cell composition of the TME." (PMID 35230974, 2022). "To understand whether LAIR1 is more highly expressed by certain immune cells in the human tumor microenvironment (TME), we searched the Cancer Genome Atlas (TCGA) database and analyzed the correlation between the expression of LAIR1 and those of several immune cell markers." (PMID 36211388, 2022). "Importantly, the LAIR1 blockade by the antagonistic antibody inhibited the activity of immunosuppressive myeloid cells and reactivated T cells from cancer patients in vitro and impeded tumor metastasis in a humanized mouse model." (PMID 36211388, 2022). "Therefore the anti-tumor effect of the anti-LAIR1 antagonist antibody in the humanized mouse model may be underestimated." (PMID 36211388, 2022). "Collagen in tumor matrix and damaged tissues is a common ligand for LAIR1 in broad spectrum, inhibiting immune cell functions after ligation, while LAIR2 was found to be a soluble protein with similar extracellular domain, which could block LAIR1 binding by competing ligands." (PMID 33841428, 2021). "In addition, the interaction between LAIR-1 and collagen can facilitate the binding of tumor cells to inhibitory molecules on immune cells to inhibit antitumor immune responses, suggesting their role in tumor immune evasion." (PMID 32563267, 2020). "A significant Bcl-2 down expression and a consequent increase in the Bax/Bcl-2 ratio in LAIR-1 overexpression tumor samples suggests that apoptosis via the regulation of the PI3K-AKT pathway and Bcl-2 family proteins may play an important role in the tumor suppressive function of LAIR-1 in vivo." (PMID 32628130, 2020).
tumor (continued). "The LAIR-1 expression level is significantly associated with tumor pathological differentiation, which suggests LAIR-1 may be a poor-differentiation biomarker for this cancer and may play a role in control tumor differentiation." (PMID 32628130, 2020). "The C1q complement molecule has the ability to bind and activate LAIR-1 to evade immune responses and expression of several members of the collagen family, such as collagens I, III, V, VI, XIII, XVII, XVIII, and XXIII is reported to be associated with tumour progression." (PMID 33396670, 2020). "LAIR1 expression may be related to the tumor environment inflammatory response." (PMID 31336593, 2019). "SP-D acts as a ligand for the inhibitory receptor LAIR-1, which inhibits the function of multiple types of immune cells, indicating that SP-D present in the tumor microenvironment may exert its immunomodulatory effect and inhibit the anti-tumor immune responses through LAIR-1 activation." (PMID 30127783, 2018). "Bioinformatic analysis of TCGA datasets indicated that the high tumor mRNA expression of MMPs, collagen I, and LAIR1 has a worse OS, suggesting a possible relationship between MMP activity and LAIR1-mediated inhibition of the antitumor T cell response." (PMID 40563506, 2025). "Conversely, in Lair1–/– GBM, the tumor collagen structure more closely resembled that of normal brain tissue." (PMID 40591413, 2025). "Additionally, distinct outcomes in the 3 pairs of mice treated with IgG or anti-Lair1 antibody suggest that a greater M2-like TAM presence might limit tumor reduction and immunological responses, possibly due to a minimal blocking effect of anti-Lair1 antibody." (PMID 40591413, 2025). "In hepatocarcinoma cells (HCCs), it has been shown that LAIR1 increases PD-L1 expression through the GSK-3β/β-catenin/MYC/PD-L1 pathway, promoting the immune evasion of tumor cells." (PMID 40563506, 2025). "Along these lines, the reported T cell exhaustion through SHP1 triggered by collagen via LAIR1 and the reduction in collagen deposition through LOXL2 enzyme suppression favors T cell tumor localization, abrogating the resistance to anti-PDL1." (PMID 40563506, 2025). "We previously showed that LAIR-1 blockade using NC410, a LAIR-2 Fc fusion protein, decreases tumour outgrowth in a humanized mouse model." (PMID 38236251, 2024). "In other studies, in vivo overexpression of LAIR-2, or LAIR-1 blocking antibodies, were used to block LAIR-1 with demonstrable anti-tumor effects." (PMID 37662958, 2023). "It revealed that LAIR‐1 expression level and LGG grade of patients are interrelated to the tumor immunity response." (PMID 35702880, 2023). "While a soluble decoy receptor, LAIR-2, is expressed in humans and competes with LAIR-1 for binding to collagen-like domains, excess LAIR ligands in the tumor often result in an immunosuppressive environment." (PMID 35230974, 2022). "The results showed that CD68 expression positively correlated with the expression of LAIR1, HAVCR2, LGALS9, and PD-1 (PDCD1) in most of the 33 tumor types." (PMID 35550532, 2022). "Currently, a dimeric LAIR-2 Fc fusion protein, NC410, which both targets the tumor ECM and promotes T-cell function through blockade of LAIR-1-mediated inhibition, is being tested in a trial as cancer immunotherapy." (PMID 35562585, 2022). "LAIR-1 expressing T cells are important players in the anti-tumor immune response, and dysfunction of T cells by signals from the TME hampers the anti-tumor activity." (PMID 34691040, 2021). "The expression of 43 collagen genes, LAIR-1 and LAIR-2 in normal (gray) and tumor tissue (red) were queried using TCGA database." (PMID 34121658, 2021). "LAIR-1 signaling has previously been shown to inhibit T cell function and LAIR-1 expressing T cells are important players in the anti-tumor immune response." (PMID 34691040, 2021).
tumor (continued). "We developed a dimeric LAIR-2 Fc fusion protein, NC410, as a novel immunomedicine to both target tumor ECM and promote T cell function through blockade of LAIR-1-mediated inhibition." (PMID 34121658, 2021). "In this study, we showed that targeting and disrupting collagen interactions with LAIR-1 by means of a dimeric LAIR-2 hIgG1 Fc fusion protein, NC410, promoted in vivo T cell activity and had a therapeutic effect in tumor models, which was dependent on T cells." (PMID 34121658, 2021). "Despite the proven regulatory role of LAIR-1 in immune cells and the high abundance of collagen molecules in the TME in promoting tumour progression, the potential roles of LAIR-1 are less investigated in BC." (PMID 33396670, 2020). "Overexpression of LAIR-1 significantly inhibited in vivo SKOV3 cell growth and reduced the tumor weight." (PMID 32628130, 2020). "The blockade of the LAIR-1-mediated inhibition by NC410 can restore the normal functionality of T and dendritic cells as well as the anti-tumor response." (PMID 33013909, 2020). "Coincidentally, this also hides tumor cells from LAIR-1-expressing immune cells such as NK cells, with LAIR-1 inhibitory signals correlating with dampened in NK cytotoxicity." (PMID 32290478, 2020). "We split patients in the training cohort in five groups, according to the tumor BCL6, CD11c, BCL2, and LAIR1 expression (high/low), and then performed Kaplan Meier analyses to determine the overall survival (OS) in the function of the expression level." (PMID 31336593, 2019). "Additionally, anti-Lair1 antibody reduced CAR T cell–M2-like MΦ interactions after approximately 35 hours and promoted increased CAR T cell–tumor interactions." (PMID 40591413, 2025). "However, the BBB’s properties change during tumor growth and inflammation, becoming progressively disrupted in these contexts, which helps open the BBB and facilitates the delivery of anti-Lair1 antibody." (PMID 40591413, 2025). "LAIR-1 is a key inhibitory receptor expressed on NK cells, and its engagement by collagen or other ligands in the TME can suppress NK cell cytotoxicity, contributing to immune evasion by tumor cells." (PMID 40806280, 2025). "Collectively, these findings suggest that LAIR1 was not predominantly expressed on tumor cells but rather on M2-like TAMs." (PMID 40591413, 2025). "Taken together, our data demonstrate that the absence of LAIR-1 signalling alone is not sufficient to control tumour growth in multiple immunocompetent mouse models." (PMID 38236251, 2024). "Taken together, we have found that complete deletion or therapeutic blocking of LAIR-1 with NC410 alone is not sufficient to induce tumour control in immunocompetent mice." (PMID 38236251, 2024). "Inhibition of TGF‐β, PD‐L1, and LAIR‐1 was recently reported to effectively control the growth of collagen‐rich mouse MC38 colon cancer and EMT6 breast cancer, leading to tumor cure and long‐term tumor‐specific protection." (PMID 37547175, 2023). "Especially, double blockage of LAIR-1 and TGF-β can support totally tumor elimination by PD-L1." (PMID 36906534, 2023). "Nonetheless, reports on LAIR‐1 expression in nonhematopoietic cells and tumor cells are rare, and its mechanism of action has not been fully clarified." (PMID 37647449, 2023). "In previous studies, LAIR-1 expression was mainly reported to be in immune cells rather than tumor cells." (PMID 36960400, 2023). "According to the visually defined cutoff that splits the NSCLC cases into high/positive versus low/negative expression (signal vs. background noise), tumor LAIR-1 positivity was detected in approximately 18% of patients with NSCLC." (PMID 36960400, 2023). "Furthermore, Horn and collaborators demonstrated that in two collagen-rich murine carcinomas, MC38 colon and EMT6 breast, the inhibition of LAIR-1 and TGF-β plus anti-PD-L1 therapy was able to control tumor growth and reshape the collagen-rich ECM." (PMID 37284199, 2023).